NAIP (NLR family apoptosis inhibitory protein)
Diseases named in the same sentence as NAIP in open-access papers (continued):
Sharing a sentence is not in itself a finding about the gene and the disease.
infection (continued). "Using this priming and infection model alongside genetic tools, we demonstrate that TNF signaling through TNFR1 licenses L. pneumophila-infected cells to rapidly and robustly undergo cell death independently of flagellin and the NAIP/NLRC4 inflammasome." (PMID 37279255, 2023). "To delve deeper into the potential contribution of the NAIP/NLRC4 inflammasome during T. cruzi infection on macrophages, we assessed intracellular parasites count at 2 h (parasite entry) and 96 h (parasite replication load) after infection." (PMID 38124741, 2023). "NAIP-/- and NLRC4-/- THP-1s treated with CASP5 siRNA showed a slight but significant decrease in IL-1β secretion following CASP5 siRNA treatment, but not CASP4 siRNA treatment, compared to control siRNA-treated cells following WT Stm infection." (PMID 35073381, 2022). "Furthermore, NAIP-/- and NLRC4-/- THP-1s treated with MCC950 secreted negligible levels of IL-1α, IL-1β, and IL-18, similar to those observed during ΔsipB Stm infection." (PMID 35073381, 2022). "Collectively, these data suggest that both the NAIP/NLRC4 and NLRP3 inflammasomes control intracellular Salmonella replication within human macrophages at both early (6 hours post-infection) and late (24 hours post-infection) timepoints." (PMID 35073381, 2022). "This could indicate that NAIP expression in THP-1 cells may be insufficient to sense the T3SS proteins in the context of bacterial infection, assuming equal levels of infection in both macrophage models." (PMID 33380493, 2021). "Surprisingly, neither NAIP silencing nor further inhibiting NLRP3 with MCC950 treatment affected caspase‐1 activation or pyroptosis during infection with SPtA 9150." (PMID 33355403, 2021). "To trace the onwards progression of the infection in the presence or absence of NAIP/NLRC4, we extended our kinetic experiments to the 24–72 h p.i. window." (PMID 33731826, 2021). "Its NAIP/NLRC4 inflammasome senses infection by Gram-negative bacteria, including Salmonella Typhimurium (S.Tm) and promotes expulsion of infected enterocytes." (PMID 33731826, 2021). "This could explain why infection events are efficiently sensed and restricted specifically by IEC NAIP/NLRC4." (PMID 31953493, 2020).
tumor (23 papers, 2008 to 2026). "NAIP may influence immunotherapy effects through tumor mutational burden and microsatellite instability." (PMID 37267294, 2023). "Various studies showed that an increase in NAIP expression was associated with tumour growth." (PMID 33023525, 2020). "Four tumor pyroptosis-associated antigens, CARD8, NAIP, NLRP1, and NLRP3, were screened as potential candidates for LUAD mRNA vaccine development." (PMID 38166691, 2024). "Four potential antigens associated with tumor pyroptosis (CARD8, NAIP, NLRP1, and NLRP3) were screened as candidate molecules for future mRNA vaccine development." (PMID 38166691, 2024). "In certain carcinoma categories, NAIP expression levels were elevated (4/33) and significantly correlated to the respective tumor stage (4/21)." (PMID 37267294, 2023). "As a result, significantly reduced NAIP will promote the death of bMECs and prevent them from being developed into tumor cells." (PMID 35812870, 2022). "Studies on the NLRC4/NAIP inflammasome using monocyte tumor cell lines suggest that in contrast to murine NAIP, human NAIP (hNaip) cannot detect cytosolic flagellin of various bacteria." (PMID 33137811, 2020). "Additional evidence of the role of NAIP/NLRC4 in the activation of T cells came from an experimental vaccination with irradiated flagellin-expressing tumor cells." (PMID 25071770, 2014). "Positive pixel analysis (insets) from 2 independent experiments demonstrated a significant 2- to 8-fold reduction in tumor cells that strongly stained for NAIP in enzalutamide-treated tumors compared to untreated tumors (P < 0.01)." (PMID 25344864, 2014). "There are a few studies on the potential role of NAIP over expression in apoptosis regulation and its clinical relevance in tumor context." (PMID 22357131, 2012). "Up to now, in few studies, the overexpression of NAIP in malignancies has been validated and considered as an effective factor for tumor development and progression." (PMID 22357131, 2012). "The antigens CARD8, NAIP, NLRP1, and NLRP3, which are associated with tumor pyroptosis, could be candidate molecules for LUAD mRNA vaccine development." (PMID 38166691, 2024). "Such as NAIP can also act as an anti-apoptotic protein by inhibiting caspase-3, and caspase-7, which may promote tumorigenesis and tumor invasion." (PMID 38678251, 2024). "Pan-cancer analysis revealed that NAIP could serve as a novel clinical prognostic marker and therapeutic target for a variety of carcinoma categories, reducing the risk of IDD in tumor patients." (PMID 37267294, 2023). "Also, NAIP expression levels were remarkably related to the tumor stage of certain carcinomas (BLCA, KICH, SKCM, and STAD)." (PMID 37267294, 2023). "Similarly, reduced expression of NAIP in LNCaP cells treated with NAIP siRNA also significantly increased tumor cells' sensitivity to T cell-mediated killing (P < 0.001)." (PMID 25344864, 2014). "The results indicated that NAIP, BIRC2, BIRC3, XIAP, BIRC5, and BIRC6 showed significantly higher expression levels in tumor tissues than in normal tissues." (PMID 37781078, 2023). "The levels of NAIP, BIRC2, XIAP, and BIRC6 were significantly elevated in the subgroups of tumor stages 1-3 compared to their levels in the normal subgroups, with no discernible differences in their levels in the subgroup of tumor stage 4." (PMID 37781078, 2023). "The effect was epithelial NAIP-mediated, as IEC-specific KO had increased AOM/DSS-induced tumourigenesis whereas knockout in the myeloid compartment had comparable tumour burden as littermate controls." (PMID 34854889, 2021). "Compared to the NCI60 analysis, we further revealed distinct expression pattern of BIRC5 and BIRC7 and synchronized expression for NAIP, BIRC2, BIRC3, XIAP and BIRC6 in multiple tumor types." (PMID 31964418, 2020).
tumor (continued). "We found that c-IAP1 (Birc2), XIAP (Birc4), Survivin (Birc5) and Livin (Birc7) were overexpressed in ESCC tissues, while NAIP (Birc1) and c-IAP2 (Birc3) were comparable between tumor tissues and adjacent non-tumor tissues." (PMID 25216531, 2014). "ProEGCG, but not EGCG, elicited a significant decrease in the growth of the EC xenografts, promoted apoptotic activity of tumour cells in the EC xenografts, and decreased microvessel formation, by differentially suppressing anti-apoptotic molecules, NOD1 and NAIP." (PMID 33023525, 2020). "In addition, NAIP expression in these malignant tissues is correlated with tumor size, but not with relapse-free survival." (PMID 30837326, 2019).
cancer (22 papers, 2007 to 2024). A tumor composed of atypical neoplastic, often pleomorphic cells that invade other tissues. "Pan-cancer analysis revealed a noteworthy association between NAIP and prognosis and immune infiltration in diverse carcinoma categories, indicating that NAIP is a promising biomarker for cancer therapy." (PMID 37267294, 2023). "Secondly, further clinical experiments on cancer patients with IDD should be conducted to explore and validate the association between NAIP and cancer patients with IDD." (PMID 37267294, 2023). "Furthermore, increased expression of OCT4 target gene NAIP/BIRC5 has been associated with therapeutic resistance in various human cancers." (PMID 33339129, 2020). "With regards to this difference levels, transient or persistent NAIP-upregulation may have occurred as a result of a hidden cancer or some other inflammatory causes." (PMID 29311650, 2018). "In the sample of anaplastic histology, GLMN and NAIP were considered marker genes for primitive vesicle-like cancer cells and endothelium-like cancer cells, respectively." (PMID 38678251, 2024). "Overall, the survival analysis revealed that levels of NAIP in different cancer types had significant prognostic implications." (PMID 37267294, 2023). "Survival analysis revealed that the expression levels of NAIP have prognostic significance in different cancer types." (PMID 37267294, 2023). "Currently, several articles have revealed that NAIP inflammasomes play a significant role in infectious diseases, auto inflammatory diseases, and cancer." (PMID 37267294, 2023). "XIAP and BIRC2 were found to express highly among different cancers while NAIP and BIRC3 were only selectively expressed in a few cell lines." (PMID 31964418, 2020). "Based on these results, the further characterization of NAIP by confocal microscopy in the human epithelial carcinoma cell line HeLa, was undertaken and unexpectedly demonstrated the presence of NAIP in the central spindle and in the intercellular bridge." (PMID 28059125, 2017). "Also, the GSEA analysis revealed that high NAIP expression was primarily concentrated in pentose and glucuronate interconversions and steroid hormone biosynthesis, which were related to various carcinoma categories." (PMID 37267294, 2023). "CTSG, NLRP9, DFNB59, APIP, SCAF11, CASP5 and NAIP showed significant downregulation across cancers." (PMID 36605187, 2022). "The role of the BIRC1 gene and the NAIP protein in cancers is not fully understood." (PMID 33673050, 2021). "Given its effect on IDD and cancer, targeted treatment of NAIP may reduce the incidence of IDD." (PMID 37267294, 2023). "Furthermore, we found that the expression of NAIP increased in some carcinoma categories, indicating the possibility that NAIP could serve as an oncogene." (PMID 37267294, 2023). "Dysregulated NAIP may contribute to the occurrence of carcinoma and neurodegenerative disorders." (PMID 37267294, 2023). "Up regulation of several IAPs like NAIP (BIRC1), X-linked IAP (XIAP, BIRC4), Survivin (BIRC5), c-IAP1 (BIRC2), c-IAP2 (BIRC3), Apollon (BRUCE, BIRC6), Livin/MLIAP (BIRC7) and IAP-like protein 2 (BIRC8) have been reported in several cancer cells as well as in serum from cancer patients." (PMID 29464049, 2018). "Of the 14 signature genes, NAIP and TP63 were considered marker genes for mononuclear phagocytes and ureteric bud-like cancer cells respectively in the sample of favorable histology." (PMID 38678251, 2024). "The analysis revealed that several members of the IAP family, including NAIP, BIRC2, BIRC3, XIAP, BIRC5, BIRC6, and BIRC7, exhibited higher expression levels in multiple cancers, including HCC." (PMID 37781078, 2023). "In this review, we highlight the role of the NAIP/NLRC4 inflammasome in host defense, autoinflammatory diseases, cancer, and cell death." (PMID 33494299, 2021).
cancer (continued). "Currently, eight human IAPs have been identified: XIAP; cIAP1; cIAP2; ILP2; BRUCE/Apollon; survivin; NAIP; and ML-IAP, and targeting a subset of these proteins has been demonstrated to promote apoptosis in cancer cells." (PMID 33205060, 2020). "Biopsy results of nasal cancer and HNC have shown that cancer cells first show consistent and strong expression of NOD1 and NAIP, while normal epithelial cells show a broader NLR spectrum with the presence of NOD1, NOD2, NLRP1, NLRP3, and NAIP." (PMID 39403369, 2024). "NAIP, BIRC2/5, and XIAP expression were related to the individual cancer stages of HNSCC." (PMID 38364254, 2024). "NAIP (NLR family apoptosis inhibitory protein), is a major anti-apoptotic protein and is targeted by miR-1 and miR-145, which induces cell death and contributes to the development of cancer." (PMID 35807355, 2022). "At the same time, we observed different localization to NAIP in cancer (compared to BPH) since not all epithelial cells were positives." (PMID 20078866, 2010). "Only NAIP mRNA revealed a slightly lower expression level in cancer tissue compared to non-neoplastic tissue, although the fold change was not significant (FC = 0.67)." (PMID 19397802, 2009).
bacterial infection (13 papers, 2014 to 2025). "The major function of the NAIP/NLRC4 inflammasome in vivo is to defend the host against bacterial infections, particularly those caused by bacteria possessing flagella and/or a T3SS, through the induction of inflammation involving the production of IL-1β and IL-18." (PMID 40158217, 2025). "However, recent reports have indicated the involvement of NLRC4 in non-bacterial infections and sterile inflammation, even though the role of NAIP proteins and the exact molecular mechanisms underlying inflammasome activation in these contexts remain to be elucidated." (PMID 38124741, 2023). "The NAIP/NLRC4 inflammasome senses bacterial infection and can be activated by treatment with a needle protein (LFn-BsaL) and protective antigen." (PMID 40892070, 2025). "The NAIP/NLRC4 inflammasome plays a pivotal role in the defense against bacterial infections, with its in vivo physiological function primarily recognized as driving inflammation in immune cells." (PMID 40158217, 2025). "The NAIP/NLRC4 inflammasome in humans is crucial to the host immune response to bacterial infections and contributes to auto-immune and inflammatory diseases in a sterile condition." (PMID 38177670, 2024). "A similar reaction was observed in cultured intestinal epithelial cells in which a bacterial infection sensed by the NAIP/NLRC4 inflammasome induce a fast myosin-dependent contraction in surrounding cells." (PMID 37417734, 2023). "The participation of NAIP in non-bacterial infection was also demonstrated in HIV-1-infected human monocyte-derived macrophages, in which hNAIP was activated by HIV-1 glycoprotein 41 (gp41) leading to the NLRC4 recruitment and IL-18 secretion." (PMID 38124741, 2023). "NAIP/NLRC4 inflammasome activation during bacterial infection occurs after recognition of their ligands by NAIP proteins." (PMID 38124741, 2023). "The well-established role of NAIP/NLRC4 inflammasome in bacterial infections involves NAIP proteins functioning as sensors for their ligands." (PMID 38124741, 2023). "NAIP expression has been detected in human monocytes and macrophages especially in the context of bacterial infections." (PMID 36189256, 2022). "In the lung, the expression of NAIP in alveolar macrophages has been confirmed by several authors in the context of bacterial infections." (PMID 36189256, 2022). "In vivo, Irf8-deficient mice are highly susceptible to bacterial infection compared with wildtype animals, confirming the critical role of IRF8 in NAIP/NLRC4 inflammasome activation." (PMID 33494299, 2021). "The NAIP/NLRC4 inflammasomes presumably evolved to initiate protective immune responses during bacterial infection." (PMID 29263322, 2017). "Since bacterial infections typically activate numerous innate immune pathways, including TLRs, it has been difficult to separate the effects of NAIP/NLRC4 activation from the downstream pro-inflammatory effects of TLR activation." (PMID 29263322, 2017). "Although the precise effector mechanisms of IL-1β and IL-18 remain to be elucidated, these cytokines have been reported to be important mediators induced by NAIP/NLRC4 to host resistance to bacterial infections." (PMID 25071770, 2014). "However, recent studies have demonstrated that NAIP/NLRC4 is also activated in non-bacterial infections, and in sterile inflammation." (PMID 36481780, 2022). "Importantly, recent studies have demonstrated a role for NAIP/NLRC4 inflammasomes in response to non-bacterial infections and sterile inflammation triggers." (PMID 36481780, 2022). "NLRP3 activation may therefore act as a “safety net” to preserve inflammasome activation during bacterial infection in the face of suboptimal NAIP/NLRC4 activation." (PMID 33380493, 2021).
bacterial infection (continued). "The identification of the critical substrates involved in the restriction of bacterial infection via the NAIP/NLRC4 inflammasomes provides important information for our understanding of the biology of these important platforms that operate for host protection against pathogenic bacteria." (PMID 31251782, 2019). "Together, these data indicate a cross talk between lysosomes and NAIP/NLRC4 inflammasomes that impact the control of bacterial infections and opens new avenues for the development of inflammasome-based therapeutic strategies for non-infectious pathologies such as tumors." (PMID 25071770, 2014). "Collectively, our findings shed light on the pivotal role of the NAIP/NLRC4 inflammasome in macrophage responses to T. cruzi infection, providing new insights into its broader functions that extend beyond bacterial infections." (PMID 38124741, 2023). "Whereas the mechanisms governing NAIP/NLRC4 inflammasome are better elucidated, primarily in the context of bacterial infections." (PMID 38124741, 2023). "Thus, NAIP is a critical inhibitor of programmed cell death in host cells, and NAIP assembles with NLRC4 to form a fully functional inflammasome, which can lead to secretion of cytokines, induction of cell death, inflammation, and bacterial infection control." (PMID 37006312, 2023). "The activation of the NAIP/NLRC4 pathway by bacterial protein ligands, in particular flagellin, and the relative contribution of the different ligands to inflammasome activation during bacterial infection are better characterized in murine macrophages than in human cells." (PMID 33380493, 2021). "NAIP/NLRC4-mediated responses are related to the restriction of bacterial growth due to the active caspase-1-mediated canonical and non-canonical effector mechanisms, highlighting the importance of this inflammasome as a host defense mechanism against a large number of bacterial infections." (PMID 25071770, 2014).
infectious disease (2 papers, 2023 to 2025). A disorder directly resulting from the presence and activity of a microbial, viral, or parasitic agent in humans. "This discovery enhances our understanding of the role of the NAIP/NLRC4 inflammasome in infectious diseases." (PMID 40158217, 2025).
hematological malignancies (1 paper, 2023). "NAIP has also been reported to be a potential molecular treatment target for hematological malignancies." (PMID 37267294, 2023).
NAIP also shares sentences with these, for which no sentence is quoted: benign prostatic hyperplasia (2 papers); lung adenocarcinoma (2); brain inflammation (1); Cluster headache (1); Diarrhea (1); disc-degeneration (1); endometrial cancer (1); glioblastoma multiforme (1); Hodgkins lymphoma (1); Legionella infection (1); leukemia (1); lung squamous cell carcinoma (1); mental retardation (1); metastatic tumors (1); myelodysplastic syndrome (1); myeloma (1); neurodegenerative disease (1); non-Hodgkin lymphoma (1); Obesity (1); parasite infection (1); periodontitis (1); polycystic ovary syndrome (1); sarcoma (1); triple-negative breast carcinoma (1); varicocele (1).